IL6 (interleukin 6)
Diseases named in the same sentence as IL6 in open-access papers (continued):
Sharing a sentence is not in itself a finding about the gene and the disease.
Obesity (continued). "Obesity is associated with a chronic state of low-grade inflammation, characterized by elevated levels of pro-inflammatory markers such as C-reactive protein (CRP), interleukin-6 (IL-6), and tumor necrosis factor-alpha (TNF-α)." (PMID 37623340, 2023). "Higher levels of circulating IL-6 have been attributed to increased fat mass and obesity, with previous work demonstrating that up to 30% of circulating levels of IL-6 may be released from subcutaneous adipose tissue in obese subjects." (PMID 36239451, 2023). "Therefore, obesity increases circulating TNF-α levels, increasing the risk of breast tumorigenesis related to insulin resistance and IL-6 synthesis." (PMID 37512149, 2023). "In an obesity model, IL-6 accelerated BMSCs senescence via the IL-6/STAT3 signalling pathway." (PMID 37891477, 2023). "Dysregulation of PVAT as a consequence of obesity leads to dysregulated production of adipokines and cytokines such as decreased hydrogen sulphide, NO, and adiponectin and increased leptin, IL-6, TNF-α, IL-12, hydrogen peroxide, and the renin–angiotensin–aldosterone system." (PMID 37372025, 2023). "In addition, FA treatment has been shown to reduce serum TNF-α levels in a mouse model of high-fat diet-induced obesity and serum IL-6 levels in formaldehyde-induced hepatotoxicity." (PMID 36836745, 2023). "The cell-mediated immune response is especially present in obesity when hypertrophic adipocytes produce proinflammatory cytokines, such as IL-6 and TNF-α, which leads to increased vascular permeability and the recruitment of cytotoxic T cells, including T cell phenotypes associated with IR." (PMID 37372966, 2023). "In addition to genetic abnormalities, proinflammatory cytokines such as tumor necrosis factor-alpha (TNFα) and interleukin-6 (IL-6) are known to be induced by obesity and high-glycemic diets." (PMID 38024815, 2023). "The primary source of IL-6 in obesity is the increase in proinflammatory type 1 macrophages (M1)." (PMID 37371961, 2023). "Thus, we selected obesity-related in vitro conditions, including glucose, insulin, TNF-α, IL-6, PA, LA, and Chol, to mimic obesity status." (PMID 37047207, 2023). "IL-6 has been characterized as an important link between obesity and coronary heart disease." (PMID 37841878, 2023). "IL-6 regulates energy homeostasis and inflammation, affecting the transition from acute to chronic inflammatory diseases, such as obesity and insulin resistance, through promoting the synthesis of pro-inflammatory cytokines and negatively regulating inflammatory targets." (PMID 37175603, 2023). "Fucosterol, a phytosterol derived from the marine brown algae Padina boryana, exhibited anti-inflammatory properties via dose-dependently down regulating pro-inflammatory cytokines (IL-1, IL-6, and TNF) and the Nrf2/HO-1 pathway and aid in the process of losing weight in obesity associated asthma." (PMID 37251328, 2023). "Moreover, obesity is linked with inflammatory cytokines such as tumor necrosis factor-alpha (TNF-α), interleukin-6 (IL-6), and monocyte chemoattractant protein 1 (MCP-1), which are particularly higher among individuals with central obesity." (PMID 38162615, 2023). "TNF-α and IL6 are two major pro-inflammatory factors in adipose tissue, and they are usually expressed at elevated levels in the serum and adipose tissue of obese individuals and involved in obesity-related systemic insulin resistance." (PMID 36501080, 2022). "Il-6-/- mice develop obesity, insulin resistance, hepatic steatosis and inflammation." (PMID 36013467, 2022). "Obesity increases systemic levels as well as cellular secretion of many cytokines and adipokines including leptin, IL6, TNFα, IGF1, fatty acid binding protein 4 (FABP4), and resistin, which are all involved in regulating the pathways associated with the development of CSCs in breast cancer tissue." (PMID 36010901, 2022).
Obesity (continued). "Our results showed that training was effective in reducing the IL-6 levels, which confirms the effectiveness and scientific validity of training in alleviating chronic low-grade inflammation in the adolescent population with obesity." (PMID 36293806, 2022). "In addition, obesity causes a pro-inflammatory state with the release of several mediators like TNF- α, IL-6, and IL-1β, promoting tumor growth." (PMID 35937803, 2022). "A possible mechanism of the associations between obesity and chronic diseases relies on the theory of inflammation and inflammatory markers such as C-reactive protein (CRP), tumor necrosis factor α (TNF-α), and interleukin 6 (IL-6)." (PMID 35501761, 2022). "Markers of inflammation such as interleukin-1 beta (IL-1β), tumor necrosis alpha (TNF-α), monocyte chemoattractant protein-1 (MCP-1 or CCl-2), and interleukin 6 (IL-6), and markers related to obesity such as leptin and insulin were measured systemically in the blood." (PMID 36387539, 2022). "Interestingly, obesity can influence the production of circulating inflammatory mediators, including the production of the cytokine IL-6 that plays a role in the development and progression of various diseases." (PMID 36291945, 2022). "Concerning the slight increase in IL-1β in PCOS-like inguinal WAT, it could be concluded that mainly IL-6 contributed to the chronic inflammatory in WAT under obesity condition." (PMID 35436959, 2022). "Therefore, it is likely that IL-6 is predominantly produced by adipocytes in individuals with obesity." (PMID 35715443, 2022). "Since IL-6 accounts significantly for obesity-related basal lipolysis in adipose tissue, we went on to test whether Phillyrin treatment could lower plasma level of glycerol, a product of lipolysis, in HFD-fed mice." (PMID 36276810, 2022). "High-fat-diet-induced obesity increases tissue inflammatory cytokines and serum TNFα and IL-6." (PMID 36432430, 2022). "AT and AT + RT were superior to RT in reducing IL-6 levels in adolescents with obesity, which is similar to previous studies and may be due to resistance training-induced muscle micro damage as well as exercise-induced fatigue." (PMID 36293806, 2022). "In addition, the enhanced production of proinflammatory cytokines TNF‐α and IL‐6 are key mediators of obesity‐mediated hepatocellular carcinoma." (PMID 35869934, 2022). "In addition, a decrease in hyaluronic acid was observed, which was caused by inflammatory cytokines interleukin (IL)-6 and tumor necrosis factor (TNF)-α that are secreted from macrophages induced in adipocytes due to obesity." (PMID 36289909, 2022). "The TLR4/NF-κB pathway may also have a significant impact on acupuncture treatment of obesity through IL-6." (PMID 36105933, 2022). "The role of IL-6 in obesity is distinct in the central nervous system and in peripheral tissues." (PMID 36105933, 2022). "Weight loss has been shown to improve inflammation in terms of several inflammatory markers associated with obesity, specifically decreases in pro-inflammatory biomarkers (CRP, TNF-α, IL-6, and leptin) and increases in the anti-inflammatory biomarker adiponectin." (PMID 35276970, 2022). "As an adipokine, IL-6 is increased in individuals with obesity and metabolic syndrome." (PMID 36362238, 2022). "Peripheral inflammation, mainly driven by IL-1β, TNF-α and IL-6, have been related to the disturbance of metabolic processes in individuals with schizophrenia (including insulin resistance, hepatic inflammation, and obesity)." (PMID 35625844, 2022). "The other cytokine that contributes greatly to low-grade inflammation in obesity is IL-6." (PMID 35276970, 2022). "In addition, there are many lines of evidence that IL-6 has also regenerative effects, transiently downregulates immune function and can actually protect from obesity and insulin resistance." (PMID 36387898, 2022).
Obesity (continued). "Obesity may increase bone resorption by upregulating pro‐inflammatory cytokines (IL‐6 and TNF‐α), which can stimulate osteoclast activity through the RANK pathway." (PMID 35304837, 2022). "Thus, blood levels of C-peptide, IL-6, and TNFa are elevated in patients with coronary atherosclerosis in the background of obesity and with unstable plaques in the coronary arteries." (PMID 36013196, 2022). "Moreover, other research showed that the deletion of CerK suppresses obesity-related inflammatory cytokines IL-6 and TNFα and reduced macrophage infiltration in adipose tissue, resulting in reduced inflammatory responses in animals fed a high-fat diet." (PMID 35745168, 2022). "Serum obesity-related factors, including interleukin-6, leptin, and free fatty acid (FA), could further affect its circulating level." (PMID 36387855, 2022). "Furthermore, obesity is associated with a low-grade inflammation status, and adipose tissue can secrete several proinflammatory factors, such as C-reactive protein, tumor necrosis factor-α, and interleukin-6, which may exert crucial functions in the pathogenesis of OPLL or OLF." (PMID 35937605, 2022). "Finally, we found that IL-6 has significant predictive value for the development of vascular damage in the diabetic population with high levels of obesity." (PMID 36139749, 2022). "The role of IL-6 in obesity-related energy regulation is also controversial." (PMID 36105933, 2022). "Therefore, we performed TNF-α, IL-1β, and IL-6 mRNA expression analysis in the bone, in order to investigate the impact of D-gal-induced aging and obesity on bone inflammatory status." (PMID 35595806, 2022). "Inflammatory factors such as interleukin 6 (IL-6), TNF-α, and monocyte chemoattractant protein-1 (MCP-1), underly chronic the low-grade systemic proinflammatory state correlated with age-associated diseases such as hypertension, obesity, and diabetes." (PMID 35721030, 2022). "Therefore, in this study, the core gene, IL-6 was used as the breakthrough point to explore the possible mechanism of acupuncture in treating obesity and pancreatic cancer by regulating IL-6." (PMID 36105933, 2022). "Perhaps, pro-death signals may simply be drowned out in some circumstances, when one considers the complex interaction between potentially anti-apoptotic factors (such as VEGF-A and IL-6) and the soup of growth factors circulating in obesity." (PMID 36038791, 2022). "Obesity is associated with low-grade inflammation characterized by an increased production of proinflammatory cytokines, such as tumor necrosis factor-α (TNF-α), interleukin-1β (IL-1β), and interleukin-6 (IL-6)." (PMID 36235574, 2022). "With the development of obesity, the adipose tissue undergoes some molecular and cellular adaptations with a significant generation of pro-inflammatory molecules such as tumor necrosis factor α (TNFα) and interleukin 6 (IL-6)." (PMID 35370992, 2022). "Indeed, individuals with obesity and T2D had a lower production of IL-2 (proliferation marker), IL-6 and TNF-α by peripheral blood mononuclear cells (PBMCs) stimulated with phytohaemagglutinin, a T-cell mitogen." (PMID 35187037, 2022). "On the other hand, a different role of IL-6 has been proposed in the context of obesity: in a randomized placebo-controlled trial, abdominally obese adults were treated with tocilizumab, the monoclonal antibody against IL-6 receptor, or with placebo, with either exercise or no exercise." (PMID 36430774, 2022). "With the aim of furthering understanding about potential metabolic links between obesity and foot pain, this cross-sectional study aims to assess whether CRP, TNF-α, and IL-6 are associated with prevalent foot pain and structural foot disorders." (PMID 35941593, 2022).
Obesity (continued). "The classically activated macrophages (M1 macrophages) from the SVF have been recognized as the main source of proinflammatory cytokines in WATs, such as tumor necrosis factor α (TNF-α), interleukin-6 (IL-6) and interleukin-1β (IL-1β), and as key participants in obesity-induced inflammation." (PMID 35646489, 2022). "Our observational study suggests that Isoflavone as a prebiotic, Lactobacillus paracasei JS1 as a probiotic, equol as a postbiotic, and IL6 as a target might exert positive effects on obesity." (PMID 36139478, 2022). "Together, these findings reveal a previously unrecognized mechanism for muscle-BAT cross talk driven by Islr, Ndufs2, and IL-6 to regulate energy homeostasis, which may be used as a potential therapeutic target in obesity." (PMID 36077405, 2022). "Insulin resistance and vitamin D deficiency related to obesity may aggravate airway remodeling and hyper-responsiveness by enhancing leptin, transforming growth factor (TGF)-β1, IL-1β, and IL-6 expression, which might then promote neutrophilic inflammation." (PMID 35626330, 2022). "Similarly, we previously reported a link between early-onset overweight and obesity with activated IL-6/STAT3 signaling, increased airway resistance and lung remodeling." (PMID 35896539, 2022). "In conclusion, the results of this retrospective case study performed in a Mexican population indicates that metabolic disorders such as: obesity, T2DM, and hypertension, as well as elevated levels glucose, IL-6, LDH and CRP are associated with the SARS-CoV-2 infection severity." (PMID 35464048, 2022). "Additionally, anthocyanins can reduce pro-inflammatory markers associated with obesity, such as CRP, IL-6, and TNF-α." (PMID 35740977, 2022). "IL-6 is an inflammatory cytokine that may have antiinflammatory or pro-inflammatory effects in a variety of physiological states, such as obesity, chronic inflammation, and endometriosis." (PMID 35866786, 2022). "Indeed, plasma IL-6 levels are raised by obesity and exercise and are considered part of an adaptive response to maintain glucose and energy homeostasis." (PMID 35470093, 2022). "Compared with the NC group, the expression of IL-6 and TNF-α in hippocampal tissues of the mice from the OC group showed a significant increase (p < 0.05); on the contrary, swimming intervention reversed the obesity-induced increase of IL-6 and TNF-α (p < 0.05; p < 0.01)." (PMID 35745162, 2022). "Many adipocytokines, including TNF-α, Resistin and IL-6, positively correlate with obesity." (PMID 35565835, 2022). "The change of IL-6 as a dependent variable was affected by IL-12, dopamine, and leptin as independent or predictor variables, and the change of leptin as a marker of obesity was greatly affected by both pro-inflammatory cytokines (IL-6 and IL-12, serotonin, and body weight." (PMID 36364892, 2022). "We found that the treatment with IAP preferentially inhibited the plasma levels of proinflammatory cytokines TNF-α and IL-6 compared to control colitis mice fed with diet-induced obesity, indicating the potent anti-inflammatory potential of this enzyme especially in obese mice." (PMID 35328382, 2022). "Furthermore, JXGTs inhibited obesity-induced inflammation by downregulating pro-inflammatory factors, such as IL-6 and TNFα." (PMID 35382381, 2022). "Similarly, among the 15 anti-inflammatory organokines, 7 (adiponectin, Omentin-1, ZAG, SFRP5, CTRP3, IL-10, and DEL-1) showed reduced levels and 8 (LCN2, VASPIN, IL-1RA, FGF21, GDF15, MANF, Irisin, and IL-6) showed elevated levels in patients with obesity." (PMID 35909571, 2022). "A recent review study has reported that Mediterranean diets, which are rich in fish, fruits, vegetables and, olive oil, may decrease inflammatory factors such as CRP, IL-6, and fibrinogen as well as risks of obesity." (PMID 35501761, 2022).
Obesity (continued). "Remarkably, overproduced interleukin-6 (IL-6) from adipose tissue macrophages (ATM) in obesity accounts for elevated basal lipolysis, which leads to production of excessive acetyl-CoA in the liver eliciting hepatic glucose production (HGP) and insulin insensitivity in mice." (PMID 36276810, 2022). "This is associated with a shift from M2-like macrophages exerting anti-inflammatory properties to M1-like macrophages secreting pro-inflammatory cytokine (i.e., TNF-α and IL-6) that contribute to a state of chronic low-grade systemic inflammation commonly documented in obesity." (PMID 35187037, 2022). "BMI and expression levels of serum inflammatory markers, namely, hypersensitive C-reactive protein, procalcitonin, and interleukin-6, were found to be significantly positively correlated, and obesity may increase the correlation between PCOS and inflammation." (PMID 35547654, 2022). "Furthermore, in a cafeteria diet-induced obese rat model, n-3 PUFA attenuated the symptoms of obesity-induced anxiety via exerting anti-inflammatory effects by decreasing IL-6 levels in the liver and TNF-α levels in the brain." (PMID 36358502, 2022). "This fact was also present in our previous study, and may be related to the lower circulating levels of IL-6, since the low grade of chronic inflammation is one of the major factors responsible for the development of insulin resistance in a context of obesity." (PMID 36139877, 2022). "Findings demonstrated that characteristics of systemic inflammation in obesity, including elevated pro-inflammatory cytokine production (TNF-α and IL-6) and upregulated NF-κB-related genes (NFKB1 and RELA), present in obesity were reduced by significant weight loss and ex vivo SCFA treatment." (PMID 35215414, 2022). "Similar to IL-6, the increase in irisin levels during obesity could mediate insulin secretion adaptation in response to increased insulin demand." (PMID 35628332, 2022). "With obesity, greater secretion of pro-inflammatory adipokines (including leptin, IL-6, TNF-α, and resistin) was observed, affecting satiety and lipid metabolism, along with a decrease in anti-inflammatory and insulin-sensitizing cytokines such as adiponectin and IL-10." (PMID 36364915, 2022). "Considering that both cell lines are directly influenced by the inflammatory state that is observed in obesity, the assessment of the expression of pro-inflammatory cytokines, namely, IL-1β and IL-6, as well as anti-inflammatory cytokines, such as IL-10, was critical." (PMID 35741327, 2022). "A target group size of 40 normal weight individuals and 40 individuals living with obesity was required for the study to be appropriately powered to detect changes in circulating cytokines (using IL-6 as the primary outcome) at > 80% power and a 5% level of significance." (PMID 35247847, 2022). "Abnormal secretion of cytokines (leptin, adiponectin, TNF-α, and IL-6) due to obesity may lead to insulin resistance in the body." (PMID 36079890, 2022). "Therefore, the aim of the present study was to perform a systematic review of the relationship between PD and obesity based on the values of the inflammation markers IL-6 and CRP detected in previously studied individuals." (PMID 36547041, 2022). "Furthermore, after adjusting for sex, age, hypertension, obesity, and IL-10, IL-4, and IL-6 levels, an increased TNF-α level was also significantly associated with sarcopenia." (PMID 36160136, 2022). "Moreover, animal studies reveal that the blockade of peripheral IL-6 trans-signaling by recombinant sgp130, induces mature-onset obesity, glucose intolerance and IR." (PMID 36498901, 2022). "Moreover, PGRN is a key adipokine that mediates HFD-induced obesity and insulin resistance via IL-6 in AT." (PMID 35909571, 2022).